FGFR2 (fibroblast growth factor receptor 2)
Diseases named in the same sentence as FGFR2 in open-access papers (continued):
Sharing a sentence is not in itself a finding about the gene and the disease.
cancer (continued). "Recognized cancer-related kinases are again observed in this set, including ERBB2, FGFR2, PTK6, RAF1 and RON (MST1R) as well as 22 understudied kinases." (PMID 29643987, 2018). "FGF2 is a molecule significantly more stable than FGF1, and binds to FGFR1, FGFR3 and, to a lesser extent, to FGFR2, allowing it to be a targeting molecule for a large group of FGFR-overexpressing cancers." (PMID 30029518, 2018). "As expected, fusions in the FGFR kinase family (FGFR2 and FGFR3) are the most frequent 5′-kinase fusions, given their high recurrence in individual cancer types." (PMID 29617662, 2018). "Among these eleven putative genes, including genes such as MYD88, FGFR2 and THBS1, stimulative or suppressive effects on cancers have been shown by the experiments." (PMID 28384236, 2017). "In ovine adenocarcinomas, VEGFR2 and VEGFD mRNA were downregulated in cancers; MMP9, TIMP1 and FGFR2 mRNA were overexpressed as compared to normal lungs." (PMID 29137669, 2017). "An intriguing cross talk between FGFR2 and CD44 likely maintains cancer stemness by reciprocally regulating their expression via differentially regulating c-Myc transcription." (PMID 27107424, 2016). "When compared with normal tissues, the expression of FGFR1, FGFR2, and FGFR4 were higher and the expression of FGFR3 was lower in cancer tissues." (PMID 27154171, 2016). "Most of the basal miRNAs targeted factors that have been implicated in the control of luminal biology (FOXA1, ERBB2), adipogenesis (FGFR2, FGFR3) and urothelial differentiation (HOX5/8/13), all of which would be predicted to be suppressed in basal cancers." (PMID 27845906, 2016). "We next examined the signal transduction pathways activated downstream of FGFR in three FGFR2-dependent (NCI-H716, SNU-16, and KATO-III) cancer cell lines." (PMID 27627808, 2016). "Among them, several genes were related in cancer pathway such as EGFR, RARA, FGF2, FGFR1, FGFR2, FGFR3, KIT, and CCND1." (PMID 27016420, 2016). "The expression of FGFR1, FGFR2, and FGFR4 were higher in cancer tissues than in normal tissues, whereas the expression of FGFR3 was higher in normal tissues." (PMID 27154171, 2016). "Imbalanced expressions of FGFR2 IIIc and PKM2 isoforms contributed to the progression and metabolism of cancer cells." (PMID 26506517, 2015). "Analysis of the cancer cell lines shows a variable, but widespread expression of MET and FGFR2, which are receptors for HGF and FGF7, respectively, across the panel of ESCC cell lines." (PMID 25884729, 2015). "HER2, EGFR, FGFR2 and FGFR3 missense substitutions were observed in 10(3.5%), 1(0.4%), 5(1.8%) and 2(0.7%) of the cancers, respectively." (PMID 25669975, 2015). "We further added to the complement of known RAS-activating mutations in observing mutations in BRAF (two MC), as well as previously unreported potentially RAS-activating alterations in FGFR2, ERBB2, and STK11, each affecting a single carcinoma." (PMID 25986173, 2015). "Meta-analysis of FGFR gene amplification status and OS in a variety of cancers was performed; 1345 patients in 6 studies for FGFR1 amplification and 1344 patients in 3 studies for FGFR2 amplification were included." (PMID 25171497, 2014). "For example, the “Cancer, Cellular Movement, Cellular Growth and Proliferation” network encompasses EGFR, FGFR2 and other key genes, such as AURKA, a cell cycle checkpoint mediator, and SPP1, LAMA3 and GJA1, which play a role in cell communication." (PMID 23383013, 2013). "Other genes down-regulated by rosiglitazone belonged mainly to two functional groups: “cancer” (RPS27A, SORBS2, STIP1, FGA, FGFR2, SSH3, EPN1) and cell death (SORBS2, STIP1, GAS2, EPN1)." (PMID 22761953, 2012).
cancer (continued). "This suggests that the mechanism by which gefitinib induces FGFR2 and FGFR3 is likely to be operative in diverse epithelial-derived cancer cell lines." (PMID 21152424, 2010). "Indeed, the expression of IGF1R, IGF2R, FGFR2-4, and de novo fatty acid biosynthetic enzymes (ACC1, FASN) correlates with ferroptosis resistance across 824 primary, adherent cancer cell lines." (PMID 40000627, 2025). "The detailed characterization of the FGFR2::SHTN1 fusion’s genetic and protein architecture, combined with our findings on Shootin1’s intrinsic oligomerization capabilities, allowed us to propose a comprehensive model for its constitutive activation in cancer." (PMID 41496852, 2025). "Additionally, FGF4, a well-known ligand of FGFR2, has been shown to stimulate EMT during cancer progression by increasing store-operated calcium entry (SOCE) and the expression of the calcium signal-associated protein Orai1." (PMID 41154409, 2025). "Furthermore, fusion transcripts involving oncogenes have been shown to exhibit increased expression in cancer, and we observed indeed strong expression of CRYBG1, FGFR2, and RTN4IP1 in MFM-223." (PMID 38391914, 2024). "The second cluster of DEGs, including FGFR2, KDR2 and MET, indicates the importance of key cancer-related pathways, including the PI3K-Akt signaling pathway, EGFR tyrosine kinase inhibitor resistance pathway, Rap1 signaling pathway, Ras signaling pathway, and MAPK signaling pathway." (PMID 38166892, 2024). "This analysis indicates that SY may inhibit FGFR2, EGFR, CAH2, KEAP1, and GSK3β, which are involved in various cellular processes related to cancer development and oxidative stress response." (PMID 38431714, 2024). "Intriguingly, this unique expression of the FGFR2-IIIb and FGFR2-IIIc isoforms in epithelial versus mesenchymal cells likely represents a specific mechanism that regulates the EMT process, which is the key step for cancer outgrowth and metastasis." (PMID 37090731, 2023). "There are many AS events involves in EMT during cancer progression, such as splicing of FGFR2, CD44, CTNND1, and ENAH and they may become therapeutic points- it is therefore timely to ask ourselves: Can these AS events in EMT be targets of cancer therapy?" (PMID 38002944, 2023). "Leveraging the single‐cell resolution of our data, we split cancer cells into FGF2 receptor (FGFR2) positive and negative cells and confirmed that differences observed in FGF2 expression were not due to the library size of the cells." (PMID 37691350, 2023). "They activate cancer cell signaling pathways and transcription factors, including IGF1/α6β4 complex, FGFR2, TIMP, DNA replication and mTOR signaling, Smad7, KLF4, and TBX2, and downstream proto-oncogenes such as MYC, MET, and CDK1, which facilitate cancer progression." (PMID 37046676, 2023). "On the whole, FGFR2-overexpressing tumors had significantly shorter survival than nonoverexpressing cancers (p < 0.001 and p = 0.019, respectively)." (PMID 37893023, 2023). "Other studies have shown that FGFR2-induced cell signaling, with AKT activation, is a driver of keratinocyte differentiation and regulates cell differentiation in ESCC and the survival/maintenance of cancer stem-like cells in ESCC." (PMID 36661697, 2023). "Furthermore, this study aims to examine the chemotherapeutic efficacy of novel formulations as inhibitors of the Her2/neu pathway and their ability to target the FGFR2/FGF2 axis mechanisms and enhance the apoptotic activity in cancer cells." (PMID 38139837, 2023). "The findings suggest that the elevated expression of FGFR2 and CEBPB in liver may contribute to cancer development in CC patients." (PMID 36996081, 2023).
cancer (continued). "The study reported that the median cancer-specific survival interval for FGFR2-rearranged patients was significantly longer (123 months) compared to that for patients without FGFR2 translocations (37 months, P = 0.039)." (PMID 36046845, 2022). "The Kd values of MEK5, which showed high affinity in %Ctrl, and EGFR, FGFR1, and FGFR2, which were further analyzed (highly correlated with cancer proliferation and metastasis), were not significant." (PMID 35454900, 2022). "In HCT116_ARNTLKO, we observed a phase-shift in differentially rhythmic transcript pairs (from cancer hallmark genes) including HIF1A and FGFR2 that were neither differentially rhythmic in HCT116_WT nor in other HCT116KO." (PMID 35552415, 2022). "In our GC patients, neither FGFR2 nor HER2 expression status differed according to the primary cancer location; however, there were some differences between histological types." (PMID 35585358, 2022). "In the same sample, we also detected another fusion with FGFR2 at the 3′ terminus: RPS24-FGFR2, thus suggesting that FGFR2 could be included in the DNA rearrangement hotspot in that cancer sample." (PMID 36009413, 2022). "Cancer types, including kidney chromophobe (KICH), KIRP, TGCT, and THYM, had neither FGFR2 CNVs nor FGFR2 mutations." (PMID 33968743, 2021). "The molecular subtypes of the study participants’ cancers were not demonstrated, but at least one FGFR3 mutation or FGFR2/3 fusion was required for study inclusion." (PMID 34206980, 2021). "Similarly, in FGFR2-positive GC, resistance to AZD4547 was abolished by EGFR, HER3, or MET inhibition, indicating that these other RTKs are responsible for cancer cell resistance to FGFR inhibition." (PMID 34830951, 2021). "We then screened human cancer cell lines for PLAC1 and FGFR2 expression by Western Blot analysis." (PMID 32499871, 2020). "Finally, GSEA results screened out several pathways involved in cancer progression, laying a solid foundation for the possible functional roles of CTLA4 or FGFR2 in HNSCC, encouraging more in-depth investigation in the future." (PMID 31894857, 2020). "A high-throughput secretome analysis has revealed that a shift from MET dependence to FGFR-2 and FGFR-3 dependence could lead to sustained cancer cell growth despite MET inhibition." (PMID 31963871, 2020). "Estimated number of patients with advanced cancer expressing an FGFR2 or FGFR3 alteration eligible for off-label use of erdafitinib by cancer type; number of studies investigating FGFR-targeting drugs for patients with cancer; and number of ongoing clinical trials on erdafitinib by cancer type." (PMID 31755953, 2019). "Results of early-phase clinical trials from different cancers suggest that selective FGFR inhibitors could be useful in treating patients with FGFR fusions and selected patients with FGFR2 amplification." (PMID 31167513, 2019). "Therefore, cancer‐related RTK become preferable targets for ADC development, e.g. RON, PTK7, FLT3, FGFR2, FGFR3, ERBB3, KIT and EPHA2." (PMID 31116512, 2019). "On the other hand, truncated versions of FGFR2 lacking S780 have been identified in cancer patients." (PMID 31146385, 2019). "One important finding of our work is that SORLA plays a major and unanticipated role in the maintenance of lysosome function in HER2-dependent cancer cells, but not in the FGFR2-amplified, SORLA-positive MFM-223 cancer cells." (PMID 31138794, 2019). "Although the mutation of serine 780 in FGFR2 to leucine clearly increases FGFR2 tyrosine phosphorylation levels and FGF1-stimulated cell migration, the role of this mutation in cancer is not clear." (PMID 31146385, 2019).
cancer (continued). "Possibly, the lack of MAPK-dependent negative feedback gives FGFR2-expressing cancer cells an advantage." (PMID 31146385, 2019). "Importantly, mesenchymal-like cancer cells expressed FGFR1(IIIc), whereas epithelial-like cancer cells expressed FGFR2(IIIb)." (PMID 31682640, 2019). "Several truncated forms of FGFR2 lacking the C-terminal tail, including S780, have been identified in cancer." (PMID 31146385, 2019). "FGFR2 (fibroblast growth factor receptor 2) belongs to the FGFR tyrosine kinase family, which is one of the most frequently altered kinase families in some types of cancer." (PMID 28384236, 2017). "Preliminary classification of the identified antigens based on their differential expression both in the cancer antigen array and shotgun proteomics experiment showed that of these 5 antigens, only COL6A1, FGFR2 and CALM1 demonstrated promise as biomarkers of PCa by both approaches." (PMID 26885621, 2016). "FGFR2 amplification may play different roles in distal gastric cancer and EGJ adenocarcinoma, as the two cancers exhibit different biology." (PMID 26933914, 2016). "The evaluation of expression and specific contribution of the two isoforms in various types of cancer is complicated by the lack of commercial antibodies that are able to discriminate between KGFR and FGFR2-IIIc." (PMID 24899248, 2014). "Among the 24 additional genes tested, the FGFR2 gene showed only marginally significant differential methylation between cancer and matched non-neoplastic tissue." (PMID 24485021, 2014). "Real-Time PCR confirmed at molecular level the overexpression of KGFR in cancer (2.5 fold, p < 0.05), while FGFR2-IIIc did not increase its expression in tumoral tissue (1.1-fold)." (PMID 24899248, 2014). "Our data suggest that FGFR2 is essential in sustaining the breast TIC pool through promotion of self-renewal and maintenance of bipotent TICs, and raise the possibility of FGFR2 inhibition as a strategy for anti-cancer therapy by eradicating breast TICs." (PMID 23300950, 2013). "Several kinds of molecular-targeting agents against FGFR2 have been developed; however, it is not clear how a cancer treatment can most effectively inhibit FGFR2 IIIb or FGFR2 IIIc, or both isoforms." (PMID 22701813, 2012). "The best way for cancer treatment to inhibit FGFR2 IIIb or FGFR2 IIIc, or both isoforms, has not been determined." (PMID 22701813, 2012). "We recently reported that shRNA-targeting FGFR2 in CRC cell lines suppressed cancer cell growth, migration, and invasion; however, no other reports have shown the usefulness of FGFR2-targeting therapy in CRC." (PMID 22701813, 2012). "Else, PRSS22 was found to be not expressed in cancer cells (EGFR/FGFR2/MET/VEGFR) of GC patients." (PMID 41497316, 2025). "C1GALT1 affects the behavior of cancer cells by altering the O-glycosylation on FGFR2, which promotes cancer cell invasiveness and stem cell-like properties.C1GALT1 also affects the epithelial-mesenchymal transition (EMT) of cancer cells, indicating its important role in cancer progression." (PMID 38699634, 2024). "We could observe some pathogenic variants in different cancer-associated genes including BRAF, FGFR2 or ERBB3 that, although not currently available in the clinical practice, may be considered for treatment in future clinical trials." (PMID 39003322, 2024). "However, despite these preclinical findings, the phase I study of BAY 1187982 produced no clinical responses in 20 patients with FGFR2-positive cancers, including one patient with oesophageal cancer, and two patients with GC." (PMID 38791079, 2024). "Comparing the abundance of FGFR2 in livers from healthy subjects versus non-tumorous (histologically normal) tissue taken from cancer patients and tumorous samples, we found significantly lower values in non-tumorous tissue but no statistically significant change in tumorous samples." (PMID 36890818, 2023).
cancer (continued). "Futibatinib, an irreversible and highly selective FGFR1–4 inhibitor that permanently disables FGFR2, has been tested in a phase II trial involving patients with advanced-stage solid tumors harboring FGFR alterations, including those with FGFR2-amplified G/GEJ cancers." (PMID 37245017, 2023). "FGFR2 extracellular domain in-frame deletions are known to cause autosomal dominant congenital craniosynostosis syndromes during growth and cause oncogenicity during cancer development in ICC, whereas the function of FGFR2 TK domain deletions was not known until now." (PMID 37964396, 2023). "Therefore, FGFR2 biomarker testing should not be limited to carcinomas of a particular histomorphological subtype." (PMID 36416959, 2023). "In addition, bile could be used to detect genomic alterations in BTC that are cancer-targeted therapy-related candidates, such as the ERBB2, FGFR1, FGFR2, FGFR3, KRAS, and WNT pathways." (PMID 36091112, 2022). "DNA FISH analysis identified hubs in multiple ecDNA+ human cancer cell lines, including COLO320-DM (MYC-amplified colorectal carcinoma), PC3 (MYC-amplified prostate cancer), HK359 (EGFR-amplified glioblastoma), and SNU16 (FGFR2- and MYC-amplified gastric cancer)." (PMID 35398879, 2022). "Currently, there is no established agent targeting FGFR2‐amplified cancers." (PMID 29573334, 2018). "Indeed, IHC quantitative evaluation indicated that the percentage of positive FGFR-2-IIIb staining area in carcinoma samples was 12.8±2.5, thus corresponding to negative signal (grade 0) (P<0.01 vs normal tissue)." (PMID 23977259, 2013). "Similarly to FGFR2, the literature concerning PEA3 and cancer is somewhat equivocal." (PMID 19410332, 2009). "Moreover, of the 42 cancer tissue samples with FGF10-positive stromal cells, 29 (69.0%) showed high FGFR2 expression in cancer cells, and there was a significant correlation between the presence of FGF10-positive stromal cells and high FGFR2 expression in cancer cells (P=0.013)." (PMID 18594526, 2008). "However, it remains unknown which of the many point mutations affecting FGFR1, FGFR2, FGFR3 or FGFR4 in cancer are druggable, that is, activating signaling while not mediating FGFR inhibitor resistance." (PMID 41361008, 2026). "Indeed, in a recent study from our lab we performed a screen using FGFR2-based splicing reporters and have identified small molecules that switch FGFR2 splicing and EMT phenotypes; therefore, modulation of FGFR2 splicing could be a potential cancer therapeutic target." (PMID 38002944, 2023). "However, GBM and KICH had the highest proportions of shallow deletions, in which FGFR2 expression was not that low, indicating that additional genetic alterations may contribute to the expression of FGFR2 in these cancer types." (PMID 33968743, 2021). "In addition, we also found that a set of 730 CpG sites located within the epi-driver genes had the same direction of change for three or more cancer subtypes, including genes that had previously proved to have biological functions in cancer progression such as EGFR, NCOR2, MAML3, TSC2, and FGFR2." (PMID 35069697, 2021). "In addition, several truncated forms of FGFR2 lacking S780 have also been identified in cancer." (PMID 31146385, 2019). "This dual role in cancer and development is not unique to SETBP1; a growing number of genes in which germline mutations cause developmental disorders, such as HRAS, ASXL1, EZH2 and FGFR2, are also known to harbor overlapping somatic mutations which drive the development of cancer." (PMID 28346496, 2017).